ENSG00000144785 (novel protein)
Gene: Protein-coding gene on chromosome 12 (56,285,916 to 56,316,059, reverse strand). Ensembl gene ENSG00000144785.
Genetic constraint (gnomAD): Loss-of-function variants: 19 observed, 31.68 expected, observed/expected ratio (o/e) 0.6, 90% interval 0.42 to 0.88. Missense variants: 253 observed, 307.65 expected, observed/expected ratio (o/e) 0.82, 90% interval 0.74 to 0.91. Synonymous variants: 101 observed, 110.96 expected, observed/expected ratio (o/e) 0.91, 90% interval 0.77 to 1.07.